HSF1 (heat shock transcription factor 1)
Diseases named in the same sentence as HSF1 in open-access papers (continued):
Sharing a sentence is not in itself a finding about the gene and the disease.
Huntington disease (21 papers, 2010 to 2024). Huntington disease (HD) is a rare neurodegenerative disorder of the central nervous system characterized by unwanted choreatic movements, behavioral and psychiatric disturbances and dementia. "Conversely, dysregulated HSF1 has been linked to many age-related neurodegenerative diseases including Alzheimer’s and Huntington’s Disease." (PMID 37707683, 2024). "As such, loss of Hsf1 has been implicated in Huntington’s disease and increasing Hsf1 activity has been proposed as a therapeutic avenue for neurodegenerative disease with broad potential." (PMID 38260373, 2024). "For example, pathological accumulation of alpha-synuclein in Parkinson’s disease or the mutated huntingtin protein in Huntington’s disease triggers HSF1 degradation." (PMID 36610605, 2023). "Our group successfully showed that HSF1 is required for the suppression of Huntington’s disease (HD), one of polyglutamine (polyQ) diseases, by crossing constitutive active HSF1 (caHSF1) or HSF1-deficient mice to R6/2 HD model mice." (PMID 36430241, 2022). "For instance, in models of poly-glutamine repeat-associated Huntington disease decreased expression of HSF1 target genes is observed and may contribute to protein aggregation." (PMID 29973287, 2018). "A preclinical model of Huntington’s disease demonstrated that constitutively active HSF1 reduces polyglutamine aggregation." (PMID 37707683, 2024). "Total HSF1 protein in brain samples exhibit a significant decline in brains of mouse AD models and in postmortem human Huntington’s Disease patients." (PMID 37707683, 2024). "For example, HSF1 is phosphorylated by CKII in Huntington’s disease affected brain cells but the same degron motif is primed by ERK1/2 and is further phosphorylated by GSK3 in cancerous cells." (PMID 35328741, 2022). "We have defined the mammalian HSR in vivo, demonstrated that this is impaired in Huntington’s disease mouse models and identified HSF1-dependent and –independent regulated pathways." (PMID 28970536, 2017). "We compared the HSR in the skeletal muscle of wild type mice with that of Hsf1 knockouts and of mouse models of Huntington’s disease." (PMID 28970536, 2017). "A recent report demonstrated that a cellular model and a mouse model of Huntington disease expressing a constitutively active form of human HSF1 exhibited reduced polyglutamine protein aggregation." (PMID 20098725, 2010). "Moreover, a constitutively active form of HSF1 suppressed polyQ aggregation in cultured cells and in mice, and enhanced the longevity of a mouse model of polyQ-based Huntington disease." (PMID 20098725, 2010). "Owing to the central role HSF1 plays in coping with stresses that disrupt protein homeostasis, HSF1 is of great interest in neurodegenerative diseases that arise from chronic protein misfolding including Alzheimer's disease, Parkinson's disease, and Huntington's disease (HD)." (PMID 33208463, 2021). "However, HSF1 activity declines with age, a change that may open the door to progression of neurodegenerative disorders such as Huntington's disease." (PMID 22216146, 2011). "Consequently, HSF1 may become a novel target for Huntington’s disease therapy." (PMID 39337461, 2024). "HSF1 is regulated in a comparable way to CREB, through stable PKA binding and, as shown here recruitment of p300, and may be likewise a target in the progression of Huntington's disease." (PMID 22216146, 2011). "Furthermore, the expression of activated HSF1 in nonneuronal tissues prolonged the lifespan of this mouse model of Huntington disease." (PMID 20098725, 2010). "In this respect, therapeutic induction of HSF1-mediated stress response by non-toxic agents, like HSP90 inhibitors and Celastroloids, is currently being explored in Huntington disease." (PMID 24212658, 2011).
Alzheimer disease (20 papers, 2014 to 2025). A progressive, neurodegenerative disease characterized by loss of function and death of nerve cells in several areas of the brain leading to loss of cognitive function such as memory and language. "HSF1 reduction is also associated with neurodegenerative diseases such as Parkinson’s and Alzheimer’s disease." (PMID 35061532, 2022). "Furthermore, increased levels of HSF1 reversed the deficiency of Purkinje cells in Alzheimer’s disease." (PMID 36610605, 2023). "Consequently, the impairment of HSF1 activity has been linked to neuronal dysfunction and cell death in a variety of neurodegenerative diseases such as Huntington's, Parkinson's, and Alzheimer's disease." (PMID 30884523, 2019). "The top 20 significant terms of the KEGG analysis included endocytosis, Alzheimer's disease, the spliceosome, the mTOR signaling pathway, RNA transport, insulin resistance, autophagy, and the Notch signaling pathway, and these pathways were associated with HSF1." (PMID 34239690, 2021). "In preclinical Alzheimer’s Disease models, HSF1, HSP70 and HSP90 proteins are expressed at low levels, a finding that recapitulates normal aging." (PMID 37707683, 2024). "The fact that exceptional longevity is associated with post-stress accumulation of HSF1 is intriguing and suggests a potential therapeutic avenue for age–related conditions such as Alzheimer’s disease which is known to have low levels of HSF1." (PMID 33846884, 2021). "Studies have shown the diminution in HSF1 levels in neurodegenerative diseases including HD, Alzheimer's disease, and Parkinson's disease and the dysregulation of HSF1 target gene expression." (PMID 33208463, 2021). "Curcumin, shown to act as an HSF1 activator, increases BDNF levels in the hippocampus and reduces memory loss in rodent models of Alzheimer’s disease (AD)." (PMID 34210082, 2021). "For instance, activation of HSF1 by the HSPC1 (Hsp90) inhibitor 17-(allylamino)geldanamycin (17-AAG) ameliorates cytotoxicity in an Alzheimer’s disease model, and activation of HSF1 by celastrol was shown to reduce toxicity in a cardiomyopathy model." (PMID 28474205, 2017). "In particular, low exosomal levels of survival factors (i.e., LRP6, REST, and HSF1) were found in Alzheimer's disease." (PMID 28912682, 2017). "Alleviation of ER stress and enhancement of heat shock response through heat shock factor 1 (HSF1) activation have previously been considered as attractive potential therapeutic targets for Alzheimer’s disease (AD)—a prevalent and devastating tauopathy." (PMID 28678786, 2017). "Intriguingly, Alu processing was accelerated by HSF1 and an increase of Alu processing was found in patients with Alzheimer's disease, suggesting that HSF1-Alu mediated gene expression plays an important role in Alzheimer's disease pathogenesis." (PMID 37153737, 2023). "Subsequently, HSF1 binds to DNA to express chaperones that initiate chaperone autophagy and degradation of abnormal proteins such as Aβ with consequent clinical improvement in Alzheimer’s disease (AD)." (PMID 35698225, 2022). "In fact, a few Hsp90 inhibitors, which promote HSF1 activity and induce Hsp70 expression, exert neuroprotection in several animal models of amyloids, including polyglutamines, Parkinson's disease, and cellular models of Alzheimer's disease." (PMID 24523910, 2014). "Accumulating evidences suggest that HSF1 mitigates α-synuclein toxicity 46, inhibits the polyglutamine aggregation 117, and prevents Tau-related pathologies 118, thereby delaying the progression of Parkinson's disease (PD), Huntington's disease (HD) and Alzheimer's disease (AD), respectively." (PMID 40520012, 2025). "Moreover, low exosomal levels of LRP6, REST, HSF1 were found in Alzheimer's disease." (PMID 28912682, 2017).
gastric cancer (19 papers, 2014 to 2025). A primary or metastatic malignant neoplasm involving the stomach. "High HSF1 expression in CAFs is strongly associated with tumor progression and poor gastric cancer patient outcome." (PMID 37254126, 2023). "Based on these results, HSF1 has been suggested as an important regulator of gastric cancer cells, and its association with various signaling and target genes has been confirmed." (PMID 34064083, 2021). "Altogether, HSF1 is associated with tumor progression and poor prognosis in gastric cancer, and it can serve as a prognostic and diagnostic biomarker of gastric cancer." (PMID 34064083, 2021). "Recent studies presented the possibility of employing HSF1 as a prognostic and diagnostic biomarker of gastric cancer." (PMID 34064083, 2021). "Kaplan–Meier analysis in patients with gastric cancer revealed that the high expression levels of HSF1 were associated with poor prognosis." (PMID 34064083, 2021). "This review suggested that HSF1 can be employed as a diagnostic and prognostic biomarker of gastric cancer." (PMID 34064083, 2021). "Moreover, it was confirmed that HSF1 is involved in the proliferation and metastasis of gastric cancer cells via an association with CagA, a major factor of H. pylori, which is known as a high-risk factor associated with gastric cancer." (PMID 34064083, 2021). "Therefore, high HSF1 levels are associated with poor survival and worse long-term survival in advanced gastric cancer stages." (PMID 34064083, 2021). "Additionally, the expression level of HSF1 is associated with advanced tumor progression in gastric cancer patients." (PMID 34064083, 2021). "Since Sp1 expression correlated with poor prognosis in gastric cancer, and our previous publication shows that triptolide can downregulate Sp1 leading to a decrease in HSP70 and HSF1, thereby causing cell death, we studied the expression of this protein in gastric cancer cells." (PMID 28192510, 2017). "This HSF1/Hsp70/BAG3 axis is associated with fortified cell resistance to treatment in glioma and gastric cancer." (PMID 40287736, 2025). "In gastric cancer, melatonin promotes apoptosis in gastric cancer cells by upregulating HSF1 protein." (PMID 40756978, 2025). "For example, two protumorigenic proteins, inhibin subunit beta A (INHBA) and thrombospondin 2 (TSP2), are secreted from CAFs to the TME via extracellular vehicles, found to be an HSF1-dependent mechanism that promotes gastric cancer." (PMID 37153737, 2023). "The role of HSF1 in these cancers is the same as in gastric cancer, which is tumor progression, including cell proliferation, invasion, and metastasis." (PMID 34064083, 2021). "The study conducted by Tong revealed that the gene expression of HSF1 was high in 21 out of 32 gastric cancer tissues." (PMID 34064083, 2021). "It was confirmed that gastric cancer patients with higher HSF1 expression had worse overall survival rates and recurrence-free survival than those with low expression in early and advanced stages." (PMID 34064083, 2021). "Particularly, in gastric cancer, it has been reported to regulate cell migration through binding to ArgBP2, and HSF1 has been shown to regulate cell migration and metastasis." (PMID 34064083, 2021). "Ginsenoside Rg3, the major compound in ginseng, was found to induce apoptosis through FUT4 inhibition via SP1 and HSF1 transcription regulation in gastric cancer cells with H. pylori CagA." (PMID 34064083, 2021). "HSF1 inhibitors in gastric cancer are still in a preclinical stage; however, this evidence suggests that HSF1 acts as a potent target for gastric cancer therapy." (PMID 34064083, 2021). "Conversely, it has also been shown that HSF1 silencing inhibits the proliferation of gastric cancer cells." (PMID 34064083, 2021).
gastric cancer (continued). "Particularly, it was confirmed that the expression of HSF1 is increased in various cancers, including gastric cancer, and an increased HSF1 expression is involved in cell death through regulating genes (Bax, caspase-3, 8, 9, and PARP) related to apoptosis." (PMID 34064083, 2021). "In gastric cancer tissue, mRNA and/or protein expression levels of HSF1 are significantly higher than those in normal tissue." (PMID 34064083, 2021). "Following this, Kim and Tong suggested that the presence of HSF1 promoted the invasion and migration activities in gastric cancer cells." (PMID 34064083, 2021). "In this review, we discuss the literature accumulated in recent years, which suggests that there is a correlation between the expression of HSF1 and prognosis of gastric cancer patients through public data." (PMID 34064083, 2021). "A study conducted by Aziz showed that HSF1, which was inhibited in gastric cancer cells, induced apoptosis through activating apoptosis-related proteins, such as Bax, caspase-3, -8, -9, and PARP." (PMID 34064083, 2021). "Recent studies have demonstrated the potential of HSF1 as a target for gastric cancer therapy through the inhibition of the transcriptional activity of HSF1." (PMID 34064083, 2021). "Additionally, HSF1 exhibits high expression in various cancers, and its high expression adversely affects the prognosis of various cancer patients, thereby suggesting that it can be used as a novel, predictive, prognostic, and diagnostic biomarker for gastric cancer." (PMID 34064083, 2021). "Particularly, high expression of HSF1 exerts the same effect in the proliferation of gastric cancer cells." (PMID 34064083, 2021). "According to these findings, the presence of HSF1 mediates cell motility, thereby effecting invasion and migration in gastric cancer cells, which needs to be explored further in vivo." (PMID 34064083, 2021). "Using several reports, we showed that HSF1 is a powerful multifaceted regulator of various cancers, including gastric cancer." (PMID 34064083, 2021). "The studies conducted by Kim, Dai, and Grunberg revealed that high HSF1 expression also contributes to poor survival in gastric cancer patients." (PMID 34064083, 2021). "Through the seven public GEO datasets, HSF1 in gastric cancer tissues exhibited high expression, which was more than that in normal tissue." (PMID 34064083, 2021). "In this review, we summarize the important studies on the activation and role of HSF1 in gastric cancer." (PMID 34064083, 2021). "In chemo-resistant gastric cancer cells, HSF1 promotes the transcription of pyruvate dehydrogenase kinase 3 (PDK3)." (PMID 34064083, 2021). "Among the evidence related to cytoskeleton and cell motility, the evidence that HSF1 regulates cell invasion and migration in gastric cancer suggests that HSF1 binds to the ArgBP2 promoter containing the sequence nGAAn." (PMID 34064083, 2021). "In gastric cancer, the overexpression of HSF1 has been observed in the patient samples, suggesting HSF1 to be the poor prognosis factor." (PMID 31878360, 2019). "The present study aimed to elucidate the clinicopathological significance and prognostic value of HSF1 expression in gastric cancer (GC)." (PMID 30326922, 2018). "Further, inhibition of Sp1 (by mithramycin) in gastric cancer cell lines resulted in downregulation of HSF1 and HSP70 expression as well." (PMID 28192510, 2017). "Because HSF-1 increased neogenin-1 expression, we determined the regulatory effect of HSF-1 on migration of gastric cancer cells." (PMID 24930499, 2014). "Taken together, our results demonstrated that HSF-1 increases gastric cancer cell motility through regulation of neogenin-1 expression, and the transcriptional activation of HSF-1 is regulated by galectin-3." (PMID 24930499, 2014).
gastric cancer (continued). "In order to further explore how galectin-3 increases neogenin-1 expression in gastric cancer cells, we focused on the transcription factor, heat shock factor 1 (HSF-1), as a major regulator of heat shock protein transcription." (PMID 24930499, 2014). "Taken together, high-expression of neogenin-1 promotes gastric cancer proliferation and motility and its expression is regulated by HSF-1 and galectin-3 interaction." (PMID 24930499, 2014). "Taken together, our results suggest that neogenin-1 increases gastric cancer cell motility, and its expression is highly regulated in gastric cancers through interactions with galectin-3 and HSF-1." (PMID 24930499, 2014). "At the same time, analysis of ferroptosis-related genes associated normal tissue and gastric cancer tissues screened out 19 FerDEGs: ten of them, i.e., TLR4, KRAS, HSF1, was highly expressed and nine of them, i.e., MUC1, PROM2, MT1G, were lowly expressed in tumor tissues." (PMID 36936437, 2023). "Recently, studies on the molecular mechanism of HSF1 have been conducted in gastric cancer." (PMID 34064083, 2021). "In the next section, we describe the biological role of HSF1 in the development of gastric cancer." (PMID 34064083, 2021). "Additionally, for the overall survival, high HSF1 expression levels in gastric cancer patients led to poor survival in advanced cancer stages (Affy ID: 202344_at and 213756_s_at)." (PMID 34064083, 2021). "In gastric cancer cells, the presence of HSF1 promotes the effect of tumorigenesis." (PMID 34064083, 2021). "Therefore, HSF1 expression is assessed for tissue-specific detection in gastric cancer, but it exhibits the advantage of predicting the expression patterns of various genes associated with gastric cancer progression." (PMID 34064083, 2021). "Consequently, this evidence also indicates that HSF1 can be established as a powerful biomarker for the prognosis and diagnosis of gastric cancer." (PMID 34064083, 2021). "Heat shock factor 1 (HSF1), presented in this review, is known to be regulated by a broad range of transcription factors, including those characterized in various malignant tumors, including gastric cancer." (PMID 34064083, 2021). "Finally, in gastric cancer cells HSF1 overexpression stimulates vimentin, N-cadherin, and Snail1 expression, and decreases the level of E-cadherin." (PMID 31752429, 2019). "Based on these studies and our results, we propose that HSF1 may be an oncogene regulating malignant progression of gastric cancer." (PMID 30326922, 2018). "The upregulation of HSF1 in gastric cancer cells stimulates the expression of MMP2, MMP7 and MMP9." (PMID 30326922, 2018). "In gastric cancer, HSF1 could promote GC cell proliferation, migration and invasion by directly interacting with MORC2 and binding to the enhancer of ArgBP2." (PMID 30326922, 2018). "Moreover, parallel and high expression of neogenin-1 and galectin-3, as well as neogenin-1 and HSF-1, was detected in human gastric cancer tissue." (PMID 24930499, 2014). "Therefore, our results strongly suggest that neogenin-1 was more detected in malignant tissues and its expression was positively correlated with both HSF-1 and galectin-3 in the malignant tissues of gastric cancer patients." (PMID 24930499, 2014). "Moreover, the parallel expression patterns of galectin-3 and neogenin-1, as well as those of HSF-1 and neogenin-1, were detected in the malignant tissues of gastric cancer patients." (PMID 24930499, 2014). "The galectin-3-increased gastric cancer cell motility was down-regulated by HSF-1 depletion." (PMID 24930499, 2014). "Moreover, we also established the parallel protein expression and co-localization of HSF-1 and neogenin-1 in malignant tissues of gastric cancer patients." (PMID 24930499, 2014). "The ablation of HSF-1 reduced the gastric cancer cell migration significantly." (PMID 24930499, 2014).